BCL2 (BCL2 apoptosis regulator)
Diseases named in the same sentence as BCL2 in open-access papers (continued):
Sharing a sentence is not in itself a finding about the gene and the disease.
choriocarcinoma (4 papers, 2015 to 2022). An aggressive malignant tumor arising from trophoblastic cells. "Bcl-2 expression decreases in line with the excessive proliferation of trophoblast cells in hydatidiform mole, leading to malignancy in invasive mole and choriocarcinoma." (PMID 26494988, 2015). "In this study, expression of Bcl-2 in choriocarcinoma was weak, so it can be presumed that there was an increase in apoptotic cell death and necrosis." (PMID 26494988, 2015). "Bcl-2 and Beclin-1 immunoexpression were studied on complete hydatidiform mole, partial hydatidiform mole, invasive mole, choriocarcinoma and normal placenta slides." (PMID 26494988, 2015). "The average total scores of Bcl-2 immunoexpression had a decreasing value, starting from partial hydatidiform mole (3.09), complete hydatidiform mole (2.36), invasive mole (1.18) to choriocarcinoma when compared to normal placenta." (PMID 26494988, 2015). "Bcl-2 expression decreases in line with the excessive proliferation of trophoblast cells in hydatidiform mole and leads to malignancy in invasive mole and choriocarcinoma." (PMID 26494988, 2015). "Our results showed that α-solanine promoted apoptosis in JEG-3 cells in vitro and altered the balance between Bcl-2 and Bax in choriocarcinoma xenografts in vivo, which may be involved in its anti-choriocarcinoma potential." (PMID 33805658, 2021).
co-infection (4 papers, 2011 to 2024). "This assay is based on the co-infection of isolated CD4+ T-cells from HIV-seronegative donors with an HIV reporter construct and a virus expressing two antiapoptotic proteins (MCL1 and Bcl2)." (PMID 37874295, 2023). "Furthermore, expression of bcl–2 and cyclin D1 is overexpressed in patients with an atypical CLL and it was found also in our patients with viral coinfection." (PMID 22567048, 2011).
colorectal adenoma (4 papers, 1996 to 2019). An adenoma that arises from the colon or rectum. "Higher expression of Bcl-2 was observed in colorectal adenomas than carcinoma suggesting that Bcl-2 might be linked to the early stage of CRC development." (PMID 31108984, 2019).
E. coli infection (4 papers, 2019 to 2025). "WB analysis demonstrated that E. coli infection markedly upregulated the expression of cGAS and Bax/Bcl2, along with the cleavage of caspase 3 and phosphorylation levels of STING, TBK1, IκBα, and P65." (PMID 41302013, 2025). "E. coli infection increased BAX and Caspase-3 p17 expression levels and BAX to Bcl-2 ratio and decreased Bcl-2 expression level; LGR-1 pretreatment reversed these phenomena." (PMID 34594329, 2021). "In contrast to Bcl-2, the increase in Bcl-XL in response to both AREG and E. coli infection was abolished by EGFR inhibition." (PMID 32082070, 2019). "E. coli infection alone led to an increase in Bcl-2 only in CBMO but not in PBMO." (PMID 32082070, 2019).
endotoxemia (4 papers, 2012 to 2024). "Endotoxemia in the sucking animals caused by increasing doses of LPS (5, 10 or 15 mg/kg/day × 5 days) in significant and dose-dependent way downregulated Bcl-2 protein level in the pancreatic acini incubated with caerulein (10−8 M) as compared to the caerulein-treated group alone." (PMID 22685683, 2012). "The aim of this study was to investigate in the pancreatic acinar cells isolated from adult animals, the effects of foregoing infant rats endotoxemia on TLR4, HSP60 and pro-apoptotic Bax, caspase-9 and -3 or antiapoptotic Bcl-2 protein expression." (PMID 22685683, 2012). "Endotoxemia dose-dependently increased TLR4, Bax, HSP60, and both caspases protein signals in the pancreatic acini, further inhibiting antiapoptotic Bcl-2." (PMID 22685683, 2012).
esophageal adenocarcinoma (4 papers, 2001 to 2024). A malignant tumor with glandular differentiation arising predominantly from Barrett mucosa in the lower third of the esophagus. "Moreover, Bcl2 the essential entity for cell survival was impacted in the three esophageal adenocarcinoma cell lines studied." (PMID 34830970, 2021).
glomerular disease (4 papers, 2012 to 2024). "WGN mitigates glomerulopathy and podocyte injury by regulating Bcl-2-mediated crosstalk between autophagy and apoptosis." (PMID 39712489, 2024). "This study for the first time demonstrates a novel action of wogonin in mitigating glomerulopathy and podocytes injury by regulating Bcl-2-mediated crosstalk between autophagy and apoptosis." (PMID 34253875, 2022). "WGN treats DKD by in mitigating tubulointerstitial fibrosis and renal tubular cell injury via regulating PI3K/Akt/NF-κB signaling pathway-mediated autophagy and inflammation, glomerulopathy and podocyte injury by regulating Bcl-2-mediated crosstalk between autophagy and apoptosis." (PMID 39712489, 2024).
glomerulosclerosis (4 papers, 2019 to 2025). A hardening of the kidney glomerulus caused by scarring of the blood vessels. "Bcl2-Bcl2 plays an important role in podocyte damage and the accumulation of ECM, leading to further glomerulosclerosis." (PMID 34576149, 2021).
gynecologic cancers (4 papers, 2017 to 2025). "In turn, consistent with previous findings, Bcl-2 upregulation has also been shown to be responsible for acquired chemoresistance to platinum compounds in gynecologic cancers." (PMID 37345024, 2023). "In gynecologic cancers, common genes regulated by prognosis-alternative miRNAs such as BCL2, EGFR, PDGFRA, and VEGFA were also demonstrated to be combinational targets for anti-cancer drugs." (PMID 32523951, 2020).
hearing loss (4 papers, 2015 to 2023). "In an animal acute LPS-induced hearing loss model, the histone deacetylase 2 Hdac2/transcription factor Sp1/miR-204-5p/apoptosis suppressor gene Bcl-2 regulatory axis mediated apoptosis in the cochlea." (PMID 37181652, 2023). "Beyond BAK1 and BCL2, it is likely that additional genomic targets will be identified for evaluation as potential circulating biomarkers for hearing loss." (PMID 34957708, 2022).
Hepatitis (4 papers, 2012 to 2020). Inflammation of the liver. "The increase in Bcl-2 and the reduction in Bax and caspase 9 indicate that astaxanthin inhibits the JNK/p-JNK pathway, and that the phosphorylation of Bcl-2 has an antiapoptotic effect in ConA-induced hepatitis." (PMID 25761053, 2015). "However, in the animal model of ConA-induced hepatitis, TNF-α could participate in autophagy through the interactions between Beclin-1 and Bcl-2 or between FADD and Atg5." (PMID 25761053, 2015).
hepatoblastoma (4 papers, 2010 to 2023). Hepatoblastoma (HB) is a malignant hepatic tumor and is the most common pediatric liver cancer. "Another study has shown that Bcl-2 siRNA-mediated gene silencing increases the sensitivity of human hepatoblastoma HepG2 cells to chemotherapeutic drugs, including 5-fluorouracil and 10-hydroxycamptothecin." (PMID 23691440, 2013).
high grade B-cell lymphoma (4 papers, 1994 to 2024). A term that refers to high grade B-cell lymphoma, not otherwise specified or high grade B-cell lymphoma with MYC and BCL2 and/or BCL6 rearrangements. "Differentiating DLBCL NOS from other LBCL types, particularly from DLBCL/high-grade B cell lymphomas (HGBL) with MYC/BCL2 rearrangements (double hit), typically involves morphological assessment, immunophenotyping, and fluorescence in situ hybridization (FISH) for BCL2, BCL6, and MYC rearrangements." (PMID 38927948, 2024).
Huntington disease (4 papers, 2023 to 2024). Huntington disease (HD) is a rare neurodegenerative disorder of the central nervous system characterized by unwanted choreatic movements, behavioral and psychiatric disturbances and dementia. "Also, BCL2 expression was upregulated in the brains of HD (Huntington’s disease) patients with longer disease duration." (PMID 36324052, 2023).
Hypercholesterolemia (4 papers, 2013 to 2022). An increased concentration of cholesterol in the blood. "Hypercholesterolemia has been associated with reduced myocardial anti-apoptotic Bcl-2 expression, which is known to have antioxidant properties." (PMID 26840416, 2016). "Furthermore, hypercholesterolemia is associated with decreased expression of anti-apoptotic Bcl-2, which plays a pivotal role in preventing apoptosis by inhibiting the activation of executioner caspases 3 and the release of mitochondrial cytochrome c." (PMID 24124583, 2013). "We assessed an increased cleaved caspase-3 activation, however, the balance of pro- and anti-apoptotic BCL-2 proteins was unaffected by isolated hypercholesterolemia." (PMID 28330474, 2017).
idiopathic scoliosis (4 papers, 2019 to 2020). A scoliosis with no known cause. "Real-time PCR was used to detect the expression of miR-424-5p and Bcl2 in IDD tissues and idiopathic scoliosis tissues." (PMID 33209193, 2020). "To explore the role and mechanism of miR-424-5p and its predicted target Bcl2 in IDD, we first analysed the expression levels of these two molecules using real-time PCR in IDD and normal tissue (idiopathic scoliosis tissues)." (PMID 33209193, 2020).
inflammatory bowel disease (4 papers, 2021 to 2024). A spectrum of small and large bowel inflammatory diseases of unknown etiology. "In the inflammatory bowel disease (IBD) induced by LPS in human colon mucosal epithelial cells (NCM460), Mor reduced apoptosis, inflammation, and oxidative stress by regulating Bax/Bcl-2, inhibiting TNF-α, IL-1β, IL-6, SOD, MDA, T-AOC, and MPO levels." (PMID 39301568, 2024).
insomnia (4 papers, 2023 to 2025). A sleep disorder characterized by difficulty in falling asleep and/or remaining asleep. "Through bioinformatic data analysis, we clarified that apoptosis signaling pathway plays an important role in the development of insomnia, and that the 3 hub genes, BCL2, SOCS3, and IL7R, are most likely involved in the development of insomnia." (PMID 39833072, 2025). "A total of 190 differentially expressed apoptosis-related genes were identified in insomnia, and BCL2, SOCS3, and IL7R were identified as important hub genes." (PMID 39833072, 2025). "Meanwhile the promotion of Bax, downregulation of Bcl‐2, and increase of apoptosis rate were observed after insomnia." (PMID 37647454, 2023). "In this study, BCL2, SOCS3, and IL7R were all under-expressed in the hippocampal neurons of the insomnia model compared with the control group, suggesting a decreased antiapoptotic capacity." (PMID 39833072, 2025). "We conducted WB experiments to detect the differences in protein expression levels of BCL2, SOCS3, and IL7R indicators in hippocampal neurons of normal control and insomnia model groups." (PMID 39833072, 2025). "In conclusion, our study verified that apoptosis is closely related to the development of insomnia, and BCL2, SOCS3, and IL7R have the potential to be therapeutic targets for insomnia." (PMID 39833072, 2025). "Overall, our results indicate that BCL2, SOCS3, and IL7R may play important regulatory roles in the development of insomnia." (PMID 39833072, 2025). "Importantly, the decrease in BCL2, SOCS3, and IL7R indexes indicated that the antiapoptotic capacity of hippocampal neurons in the insomnia model group was weakened, and thus it is highly likely that BCL2, SOCS3, and IL7R are important targets in the development of insomnia." (PMID 39833072, 2025). "Although BCL2 has been studied in the context of sleep deprivation, SOCS3 and IL7R have not yet been explored in insomnia." (PMID 39833072, 2025).
invasive ductal carcinomas (4 papers, 2005 to 2013). "The present study demonstrated a close correlation between Bcl-2 and p27 protein expressions regarding invasive ductal carcinoma of the breast." (PMID 16839413, 2006).
ischemic heart disease (4 papers, 2014 to 2022). "Notably, an imbalance in the ratio of anti-apoptotic to pro-apoptotic Bcl-2 proteins appears causal in the development of cardiovascular disease, including ischemic heart disease, so relationship to study drug cannot be excluded." (PMID 25285531, 2014). "A strong negative correlation of Sirt1 and the Bax/Bcl-2 ratio of gene expression was also observed in patients with coronary artery disease." (PMID 33250679, 2020).
latent infection (4 papers, 2014 to 2025). "In our BH3 profiling study, we found that mature human peripheral blood B cells depend solely on BCL-2 for survival while EBV latent infection further suppressed apoptotic priming during outgrowth by initially upregulating MCL-1, followed by BFL-1." (PMID 28425914, 2017). "One possibility is that HSP70 increased during latent infection and can act to stimulate the expression of Bcl2 via AKT." (PMID 25772624, 2015). "Consistent with this, and the known increase in cIL-10 during HCMV latent infection of CD34+ cells, latently infected CD34+ cells also showed extensive increases in STAT3 phosphorylation and concomitant increases in the expression of Bcl2 and HSP70." (PMID 25772624, 2015).
lung disease (4 papers, 2013 to 2021). "The increasing expression of Bcl-2 and Bcl-xL inhibits autophagy and bacterial killing in human macrophages, suggesting that targeting the Bcl-2/Bcl-xL-Beclin 1 interaction may improving resistance to infection in patients with advanced lung disease." (PMID 32983259, 2020). "Moreover, they found methylation frequencies of 7 genes including bcl2 were significantly higher in stage I NSCLC than in non-cancerous lung diseases." (PMID 33773561, 2021). "The methylation frequencies (29.70–64.36%) of 7 genes (MYF6, SIX6, SOX1, RARB, BCL2, PHOX2A and FOLX2) in stage I NSCLC were significantly higher compared with those in non-cancerous lung disease controls (P<0.05)." (PMID 23599765, 2013). "The methyaltion frequencies of 7 genes: MYF6, SIX6, SOX1, RARB, BCL2, PHOX2A and FOLX2 were significantly higher in stage I NSCLC than in non-cancerous lung diseases." (PMID 23599765, 2013). "This study showed that 7 genes (MYF6, SIX6, SOX1, RARB, BCL2, PHOX2A and FOLX2) were frequently methylated in 101 cases of patients with stage I NSCLC, while rarely methylated in 30 patients with non-cancerous lung diseases." (PMID 23599765, 2013). "A panel of 4 genes (MYF6, SIX6, BCL2 and RARB) was able to diagnose stage I NSCLC from non-cancerous lung diseases with a sensitivity of 93.07% and a specificity of 86.67%." (PMID 23599765, 2013).
male infertility (4 papers, 2018 to 2025). The inability of the male to effect fertilization of an ovum after a specified period of unprotected intercourse. "Visualization of this complex environmental health dataset illuminates candidate genes (BAX, BCL2, and SOD2) and phenotypes (male gonad development, apoptosis, and spermatogenesis) connecting the chemicals to male infertility, and thus may represent critical intermediate molecular mechanisms." (PMID 39104826, 2024).
mastitis (4 papers, 2019 to 2026). Inflammation of breast tissue during lactation or postpartum due to an obstructed duct or infection. "Therefore, we suspect that m6A modification of BCL2 is involved in the process of apoptosis in mastitis." (PMID 34200743, 2021).
metastatic colorectal cancer (4 papers, 2001 to 2020). "Survivin together with Bcl-2 was downregulated by yttrium-90 treatment of chemorefractory liver-dominant metastatic colorectal cancer." (PMID 25140197, 2014). "The clinical relevance of bax and bcl-2 protein expression has been investigated in 84 patients with recurrent or metastatic colorectal cancer submitted to a chemotherapy regimen including methotrexate and fluorouracil/leucovorin." (PMID 11237386, 2001).
Miscarriage (4 papers, 2023 to 2024). A pregnancy that ends at a stage in which the fetus is incapable of surviving on its own, defined as the spontaneous loss of a fetus before the 22th week of pregnancy. "A strong expression of Bcl-2 was observed in 31% of women with miscarriage as compared to 40% strong and 40% weak expression in the control group." (PMID 39408839, 2024). "Exposure to PS-NPs triggered the activation of Bcl-2/Cleaved-caspase-2/Cleaved-caspase-3, resulting in excessive apoptosis in the mice’s placental tissues and subsequently inducing miscarriage." (PMID 39195655, 2024). "Also, it is observed that the process of apoptosis in trophoblastic cells of the miscarriage group was significantly higher because the level of Bax was higher, while the expression level of Bcl-2 (an anti-apoptotic protein) was markedly reduced." (PMID 37727391, 2023).
mood disorder (4 papers, 2012 to 2022). A cognitive disorder a disturbance in which the person's mood is hypothesized to be the main underlying feature. "In encephalic regions closely associated with mood disorders, namely the PFC, NAc and Hip, altered duration of lighting led to upregulated HINT1, accompanied by increased BAX and decreased BCL-2." (PMID 29937721, 2018).